CD4 (CD4 molecule)
Diseases named in the same sentence as CD4 in open-access papers (continued):
Sharing a sentence is not in itself a finding about the gene and the disease.
tumor (continued). "More MDSCs and Tregs in the GL261-pirb+ tumor sites, while fewer CD8 + T cells and CD4 + T cells were observed." (PMID 36853330, 2023). "An increased infiltration of CD4+ and CD8+ lymphocytes were observed in the tumor for all three viruses, both in the treated and the untreated side, more prominently with T-mfIL12 and T-mIL12-IRES than T-01." (PMID 36966232, 2023). "The T-cell markers CD3, CD4, CD8 were specific to subsets of lymphocytes predominantly located in stromal tissue adjacent to tumour epithelium, but with varying amounts of intra-tumoural expressing T-cells." (PMID 37527282, 2023). "New studies have highlighted the crucial importance of collaborative interactions between antigen-specific CD4+ and CD8+ T cells in anti-tumor immunity." (PMID 38037114, 2023). "Tumor-infiltrating lymphocytes (TILs) TILs are present in the TME of GBM, including CD4+ and CD8+ T-cells, and CD4+CD25+FoxP3+ Tregs." (PMID 37165457, 2023). "Regarding CD4+ T cells, in colon cancer, TCF1 expression in Tregs suppressed tumor growth by inhibiting the transcription of FoxP3-regulated genes." (PMID 36239683, 2023). "It was shown that tumor infiltration of both CD8 + and CD4 + T cells was enhanced, and NK cells were activated with the diminution of MDSCs and Foxp3 + Treg cells (immune tolerance)." (PMID 36810079, 2023). "In another study, CD4 T cell-derived IL-21 induced the expansion of strongly cytolytic CX3CR1+ CD8 TILs, which promoted tumor control." (PMID 37189417, 2023). "Mechanistic studies regarding the rWTC-MBTA vaccination revealed enhanced activation of APCs, heightened CD4+ and CD8+ T-cell mediated response, generation of immune memory along with tumor specific cytotoxicity." (PMID 37936697, 2023). "CD4 and CD8 T cell frequencies are normal in lung and lung-draining lymph nodes after tumor seeding." (PMID 37426658, 2023). "Lactobacillus plantarum prolongs survival of tumor-bearing mice by enhancing effector CD8+T cell function, CD4+T cell differentiation, and NK cell intratumoral infiltration." (PMID 37035188, 2023). "We characterized the T cell responses driven by the EGFRvIII-DBTE in an activation assay against U87vIII cells and observed that EGFRvIII-DBTE induced CD69 activation in T cells and anti-tumor cytokine release in both CD8+ and CD4+ T cell populations." (PMID 36915911, 2023). "We demonstrated that PRV treatment can enhance the infiltration of CD4+ T cells, CD8+ T cells and neutrophils into a Hepa 1–6 tumor microenvironment." (PMID 37891570, 2023). "Meanwhile, flow cytometry analysis showed that the proportion of MDSCs and M2-like macrophages in TME was also significantly reduced, and the infiltration of CD4+ and CD8+T cells was increased, which exert an anti-tumor effect." (PMID 36675491, 2023). "The results showed that compared to the control group, BZD significantly increased the number of CD4+ and CD8+T cells in the spleen of tumor-bearing mice, promoted T cell activation, and increased IFN-γ level." (PMID 37799727, 2023). "We found that infiltration of CD4‐positive and CD8‐positive human T cells were significantly increased in the tumor tissues of the mice treated with anti‐GM2 7 × 19 CAR‐T cells compared to those with Conv." (PMID 37031457, 2023). "In vivo, AsC suppressed the tumor growth of LLC and B16F10 allograft significantly in mice, and promoted the infiltration of CD4+ T and CD8+ T cells in tumor tissues." (PMID 38132921, 2023). "Thus, we hypothesize that the anti-tumor role of cytotoxic Tr1 cells in this context is driven by the ability of PD1 blockade to preferentially enhance production of Th1 cytokines such as IFNγ over IL10 in Tr1-like CD4 T cells from human cancer samples." (PMID 37654482, 2023). "CD3+, CD4, CD4/CD8, and CD8+ levels in the tumor control and paclitaxel groups differed significantly (P = 0.05)." (PMID 36902470, 2023).
tumor (continued). "IFNγ is secreted primarily by innate NK and NKT cells, and adaptive Th1-skewed CD4 and cytotoxic CD8 T cells, and IFNγ is a necessary component of an efficacious anti-tumor immune response." (PMID 38130991, 2023). "The result showed that the proportion of live CD45+, CD45+TCRβ+, CD45+TCRβ+CD4+, and CD45+TCRβ+CD8+ cells were increased in TNFR2-/- tumor tissues." (PMID 36923938, 2023). "Immune cells such as macrophages, dendritic cells, NK cells, B cells, CD4 + T cells, and CD8 + T cells can bolster anti-tumor immune responses, shielding us against malignant cells." (PMID 37945918, 2023). "The treatment led to primary tumor suppression (tumor volume ≈ 0 mm3) and an increase in CD8+ and CD4+ T cells, 9.3- and 10.3-fold higher compared to control groups, followed by a reduction of metastasis." (PMID 37238966, 2023). "In the ABLATIVE study, six to eight months after single-dose pre-operative PBI, a decrease of CD3, CD4, and CD8 TILs was found in tumor tissue." (PMID 37161377, 2023). "Results showed that there were circulating multifunctional neoantigen-specific CD4 and CD8 T cell responses, and tumor-infiltrating T cells showed an increase." (PMID 37415744, 2023). "Meanwhile, TGF-β converts naïve CD4+ T cells into Treg cells, limits effector T cell proliferation and function, and augments FoxP3 and CTLA-4 expression, hence facilitating tumor growth and metastasis." (PMID 37868967, 2023). "CD4+ T cells assist in activating other immune cells, while CD8+ T cells directly recognize and eliminate tumor cells." (PMID 38045830, 2023). "As activated CD4+ and CD8+ T cells would secret TNF-α to exert cytotoxic effects on tumor cells, we performed flow cytometry analysis to detect TNF-α." (PMID 37370831, 2023). "Liver metastases, on the other hand, showed a lower correlation in the densities of CD4 and CD8 T cells across tumor borders." (PMID 37768208, 2023). "Components of the adaptive immune system such as CD4+ and CD8+ T cells, which recognize antigens and subsequently induce an effective immune response against cancer, can be found infiltrating the tumor." (PMID 37104271, 2023). "Regulatory T cells (CD4+CD25+) were purified from control and MIP treated tumor draining lymph nodes by magnetic-activated cell sorting." (PMID 37122749, 2023). "In combination with an anti-PD1, the tumor even shows regression, dependent on the infiltration of CD8+ and CD4+ T cells." (PMID 37143666, 2023). "Sample overview including TILs/fragment, CD4 and CD8 frequencies, and ICS tumor stimulation for the three TME conditions." (PMID 37359554, 2023). "Tregs, in addition to inhibiting CD4+ and CD8+ T cells from becoming activated, enhance angiogenesis to improve the delivery of oxygen and nutrients to the tumor site." (PMID 38096229, 2023). "In HCC, CXCL9 is associated with the recruitment of tumor-infiltrating immune cells (mainly CD4+ and CD8+ lymphocytes) shaping the TME and possibly amplifying anti-tumor responses of cytotoxic T cells." (PMID 36982370, 2023). "Current tumor immunology studies suggest that CD8+ T cells, CD4 memory activated, and Dendritic cells activated play a protective role in tumors, and the higher their infiltration levels, the better the patient prognosis." (PMID 37588995, 2023). "Furthermore, the amount of α-smooth muscle actin (α-SMA)+ fibroblasts at the tumor invasive front positively correlated with the number of macrophages (MØs), but negatively correlated with that of tumor-infiltrating granzyme B+ immune cells, and CD4+ and CD8+ T cells." (PMID 37254126, 2023). "DHA combined with anti-PD-1 treatment promoted CD4+ T cell infiltration in spleen and CD8+ T cell infiltration in tumor tissue." (PMID 37355637, 2023). "Bufalin potently enhanced the infiltration rates of CD4+ and CD8+ T cells in tumor tissues, signifying that bufalin augmented anti-tumor responses." (PMID 36903477, 2023).
tumor (continued). "Related studies also found that in the anti-tumor immune environment, CD3+, CD4+ and CD8 + cells and CD4+/CD8+ will have a direct impact on immune function." (PMID 37005450, 2023). "To characterize immune populations within the tumor microenvironment, we evaluated the expression of CD3, CD4, CD8, FOXP3, and CD68." (PMID 36672477, 2023). "Our results found significant correlations of reduced CD4+ T-lymphocyte content, reduced CD4+/CD8+ ratio, and increased CD8+ T-lymphocyte content with poorer tumor tissue differentiation." (PMID 37206348, 2023). "We also observed significantly more EdU+CD8+ T cells and EdU+CD4+ T cells in the dLN 48 h after tumour inoculation at ZT9 compared with ZT21, demonstrating a higher T cell proliferation rate after ZT9 tumour inoculation." (PMID 36470303, 2023). "Besides, the endogenous tumor specific antigens naturally arisen by somatic mutation along with those introduced by genetic manipulation of the cell line are cross-primed by the indirect pathway of antigen presentation stimulating CD8 T cell and CD4 T cell cytotoxic activity." (PMID 37033927, 2023). "Early clinical trials primarily targeted CD25 as a marker for Treg, drugs such as denileukin and daclizumab have been reported to reduce the proportion of CD4+CD25+Treg and enhance the response rate to tumor vaccine." (PMID 38250084, 2023). "Anti-PD-1/CTLA-4 treatment inhibits tumor progression in a CD4+ and CD8+ T cell-dependent manner, with CD4+ and CD8+ T cells working in an orchestrated fashion to control tumors." (PMID 37449205, 2023). "More precisely – alterations in the size and activation status of TAMs and MDSCs contributed to an enhanced influx into tumor nodules of CD8+, NK, NKT and CD4+ cells." (PMID 37033926, 2023). "This reveals that A2AR is highly expressed on all tumor-infiltrating lymphocyte subsets including Natural Killer (NK) cells, NKT cells, γδ T cells, conventional CD4+ and CD8+ T lymphocytes and on a MHCIIhiCD86hi subset of type 2 conventional dendritic cells." (PMID 37914685, 2023). "In keeping with this observation in the RT and αCD40 combination treated mice, we found a culmination of APC activation and an increase in the numbers of both CD4 and CD8+ T-cells both systemically and within the TME, during the peak of tumor regression." (PMID 37332616, 2023). "In the current study, cell counts of CD45+, CD3+ T, CD3+CD4+ Th, CD3+CD8+ CTL, CD16+CD56+ NK and CD19+ B sharply decreased not only with the cancer diagnosis, but also with the tumor moving toward advanced stage." (PMID 38102684, 2023). "Several recent studies demonstrate that human CXCL13+CD4+ and CXCL13+CD8+ T cells, which are also phenotypically similar to exhausted or hyperactivated T cells, are tumor antigen–specific and mediate responses to the anti-PD-1 therapy." (PMID 37546701, 2023). "These DCs are particularly effective in presenting tumor antigens through MHC class I (cross-presentation) and MHC class II molecules, thus eliciting strong CD8+ and CD4+ antigen-specific T cell responses." (PMID 37626903, 2023). "Researchers further analyzed that T cells isolated from the tumors of mice bearing SCLC, CD4+ TILs, and CD8+ T TILs were observed to infiltrate the tumor, while few FOXP3+ TITLs gather in the tumor bed." (PMID 36776832, 2023). "We noticed that the presence of CD127+/KLRG1+ CD8 T cells was positively correlated with that of CD20+ B cells and CD4+ T cells in both post-NAC and post-NAPC tumor tissues, indicating a possible intercellular interaction between these cell types." (PMID 37231145, 2023). "It is homologous to CD4 but has a greater affinity for MHC class II molecules; additionally, LAG-3 can bind to LSECtin and FGL1, which are expressed by some tumor cells." (PMID 36960057, 2023). "LAG3 is strongly associated and synergistic with PD-1 as it is co-expressed with this immune checkpoint on CD4 and CD8 T cells which blocks the anti-tumor immune response." (PMID 38299143, 2023).
tumor (continued). "Tumor-infiltrating lymphocytes (TILs) were isolated from control and NR4A1-treated mice (low-dose groups), and the percentage CD8+ and CD4+ T-cells and Treg cells were determined by flow cytometry." (PMID 37847301, 2023). "We found that high PD-1-positive-expressed CD4+ and CD8+ T cells within the 100-μm distance to the tumor cells during the combination treatment were significantly associated with better OS." (PMID 37275884, 2023). "In a B16F10 subcutaneous tumor model, OX40 expression was significantly increased, with nearly 2-fold upregulation, on infiltrating CD4+ T cells after intratumoral injection of CpG, a ligand for TLR9." (PMID 37700338, 2023). "This analysis showed that the percentage of CD4+ CD27+ cells and IDO+ monocytes remained independent predictors of tumor progression." (PMID 36900156, 2023). "Based on scRNA-seq results, we conducted mIF staining of T cells (CD3, CD4 and CD8), macrophages (CD68) and CCL4, which further indicated the differential distribution of immune cells between tumor thrombus and primary tumor." (PMID 37244923, 2023). "Kaplan–Meier analysis, which was based on the cutoff value of the density of CD4 + T cells and CD8 + T cells in different tumor areas, was conducted to assess the variables in OS among different groups." (PMID 37277702, 2023). "The results then showed that in the tumor tissues, the group of MT CAR-T cells treatment showed higher CD4 and CD8 infiltration compared to the group of anti-MSLN CAR-T cells." (PMID 37359558, 2023). "The numbers of splenic CD4+ and CD8+ T cells were slightly but significantly declined in tumor-bearing Zeb1-dcKO mice, consistent with the decreased numbers of splenic cDC1." (PMID 37863917, 2023). "CD4+ T helper cells support the immune response of CD8+ T cells and B lymphocytes, and are crucial for initiating and maintaining protective anti-tumor immunity." (PMID 37238744, 2023). "The tumor-rich sections showed increased TLT-1 and reduced CD8 staining as compared to sections with poor tumor density; however, CD4 T cells appeared to have the opposite pattern." (PMID 36305874, 2023). "Our cell-cell interaction analysis highlighted CXCR5+ B cells as the dominant antigen presenting cells in ICI OT-R TME, presenting antigens to both tumor-reactive CD8 T cells and CD4 Tfh cells and through MHC I and MHC II pathways, respectively." (PMID 37435085, 2023). "The main telomerase-targeting vaccine (GV1001) binds to multiple HLA class molecules to stimulate the release of CD4+/CD8+ T-cells and target the tumour." (PMID 37686543, 2023). "In a preliminary vaccine study, anti-CD27 agonist combined with PD-1 blockade re-enforced CD4+T-cell help and optimized CTL responsiveness for effective tumor elimination." (PMID 37345056, 2023). "To determine the relative contributions of T cell subsets to the improved tumor inhibition by SRA-silenced DCs, we removed either CD4+ or CD8+ T cells from mice using respective depleting antibodies." (PMID 36793731, 2023). "Meanwhile, the nanoprobes can also promote the recruitment of immune cells such as CD4+ Th and CD8+ CTL cells to accumulate in the tumor tissues to inhibit the tumor growth through the cytokines secretion and ferroptotsis enhancement." (PMID 36597067, 2023). "Tumor growth was significantly reduced and the tumor site exhibited a remarkable increase in TI -CD8+ cells, increased IFN-γ expression in effector CD4+ and CD8+ T cells, and a remarkable decrease in Tregs." (PMID 37828948, 2023). "The COX-2-PGE2 pathway induces tumor immune evasion by regulating myeloid-derived suppressor cells (MDSCs), lymphocytes (CD8+ T cells, CD4+ T cells and natural killer cells), and antigen presenting cells (APCs)." (PMID 36776289, 2023). "We detected higher percentages of CD8+IFN-γ+ and CD4+IFN-γ+ T cells, which paralleled a better control of tumor growth in mice bearing LLC-SULT2B1b tumors." (PMID 36792589, 2023).
tumor (continued). "CD4+ T cells have important roles in antitumour immunity, which is largely attributed to the priming of CD8+ T cells to achieve the tumour killing effector function." (PMID 37628721, 2023). "TILs, including CD4+ T cell, CD8+ T cell, and Treg cell, cooperate with tumor cells through the release of chemokines and cytokines acting as important tumorigenic and prognostic factors." (PMID 36043478, 2023). "This depends on both CD4+ and CD8+ T cells, as depletion of either subset before or after vaccination led to tumor outgrowth following subsequent challenge." (PMID 37655661, 2023). "Results also showed an increased proportion of tumor-infiltrating lymphocytes (CD3+) and of CD8+ and CD4+ T cells for L-Ce6 MNs together with laser irradiation." (PMID 37238966, 2023). "We showed that genetically delivered IL-15/IL-15Rα acts on NK cells, CD4+ and CD8+ T cells during PBL-mediated tumor cell killing." (PMID 37923822, 2023). "We next investigated tumour infiltration by CD45+ cells, CD8+ T-cells and CD4+ T-cells using RNA-seq deconvolution, and independent analysis of IHC staining for these markers." (PMID 37013636, 2023). "Research from Dr. Sam W. Lee’s group at Yale School of Medicine revealed that the in vitro inhibition of CD4+ T cells by MDSCs was reversed by treatment with antibodies targeting VISTA and in VISTA–/– syngeneic murine tumor models." (PMID 37795437, 2023). "We show that administration of naive CD4+ T cells polarized to Th2 cells, using IL-4, IL-2 and anti-IFN-γ antibody, not only prevented tumor growth, but reversed growth curve of colon and pancreas cell-derived allograft tumors." (PMID 36376448, 2023). "The significant decreases in the percentage of CD4+ and CD8+ T cells in the spleens of 4T1 tumor–bearing mice were observed following pharmacogenetic activation of CeMCRH neurons." (PMID 37847562, 2023). "Paradoxically, an abundance of intratumoral CD4+ and CD8+ T cells were related to a high tumor grade and shorter survival of the patients." (PMID 37047824, 2023). "3',4',7,8-THF shows tumoricidal activity and increased levels of CD3+CD4+ and CD3+CD8+ T-cells in the tumor and tumor-draining lymph nodes (TDLNs) in the murine tumor model using 4T1 and MC38 cells." (PMID 37924094, 2023). "Nevertheless, both CD4 and CD8 ACT therapies substantially increased the number of myeloid cells in HCmel12 CRISPR-ctrl and HCmel12 Jak1-KO tumours." (PMID 37316667, 2023). "Increased migration of CD4+, CD8+ T cells, and cytotoxic T lymphocytes/Treg ratio at the tumor site was observed, and inhibited tumor progression." (PMID 37106400, 2023). "Results indicated that the proportions of Tregs in CD4+ T cells and of CD3+ T cells in lymphocytes in PBMCs of tumor‐bearing mice treated with NU7441 were also significantly reduced." (PMID 36373232, 2023). "The results displayed that the expressions of OSBPL3, OSBPL5, SOBPL7, and OSBPL10 were significantly correlated with tumor purity, B cell, CD8 + T cells, CD4 + T cells, macrophages, neutrophils, and dendritic cells infiltration levels." (PMID 36918840, 2023). "Within the tumor microenvironment, increases in intratumorally activated DCs and IFN-γ-producing CD4+ and CD8+ T cells were found in the group inoculated with the MIF-deficient cancer cells." (PMID 36672343, 2023). "However, we found that memory B cells (p = 0.006), CD8 T cells (p = 0.001), memory resetting CD4 T cells (p = 0.001), activated NK cells (p = 0.002), M2 macrophages (p = 0.028), and activated mast cells (p < 0.001) were significantly more abundant in tumor than in normal samples." (PMID 37428291, 2023). "Our result showed that the proportions of CD3+CD4+, CD3+CD8+, and MAIT cells in the DM‐CRC group in tumor significantly decreased compared with that in the CRC group." (PMID 36999930, 2023).